TNF (tumor necrosis factor)
Diseases named in the same sentence as TNF in open-access papers (continued):
Sharing a sentence is not in itself a finding about the gene and the disease.
abscess (continued). "In the Hurley stage II/III, nodules, abscesses, and fistulas are further formed, characterized by a massive infiltration of inflammatory cells and pro-inflammatory cytokines, including IFN-γ, TNF-α, IL-1, IL-17, and IL-12/23." (PMID 35409118, 2022). "S4) and found a similar pattern as our neutrophilic abscess area results whereby neutrophil numbers were markedly decreased in the skin of TNF−/− and TNFR1−/− but not TNFR2−/− mice compared to WT mice." (PMID 37327341, 2023). "Unexpectedly, we found that the neutrophilic abscess area (as denoted by the black arrows) was abrogated in TNF−/− and TNFR1−/− but not TNFR2−/− mice compared to WT mice." (PMID 37327341, 2023). "Topical injection of anti-TNF agents has been described in the treatment of long-standing perianal fistulizing CD in the absence of an abscess." (PMID 32974357, 2020). "Alternatively, it is possible that anti-TNF therapy is the major driver of fistula healing, and that local surgical drainage along with seton placement does not provide additional benefit, particularly in the absence of drainable abscesses." (PMID 38491943, 2024).
alcoholism (46 papers, 2008 to 2025). "Cytogenetic band 6p21, the chromosomal location of TNF, has recently been associated with chromosomal aberrations in alcoholism." (PMID 18822146, 2008). "Within the group subjected to alcohol, there was a significant increase in levels of pro-inflammatory cytokines (IL-4, IFN-γ, TNF-α), indicating the role of inflammatory processes in the progression of initial alcohol-related liver damage." (PMID 38672817, 2024). "On the other hand, liver function impairment is related to increased cytokine (with the exception of the TNF-α) and MDA levels, a finding shared by the vast majority of authors involved in research related to the alcoholism-associated inflammatory response." (PMID 36009045, 2022). "Immunosuppressive conditions were detected in 11 of 59 (18.6%) patients: 10 of 11 (91%) for anti-TNF drugs and 1 patient (9%) referred alcoholism." (PMID 34758023, 2021). "Enrichment analysis of the list of TRIB2 upregulated transcripts showed a significant enrichment for genes involved in pathways in cancer and TNF signaling, alcoholism and transcriptional misregulation in cancer." (PMID 33316942, 2020). "In the KEGG pathway enrichment analysis, DE-mRNAs were primarily involved in viral carcinogenesis, alcoholism, the tumor necrosis factor(TNF)-signal pathway, the Nuclear Factor-KappaB(NF-kappaB) pathway and the SLE pathway." (PMID 32228489, 2020). "It would have been beneficial to compare our results to previous studies if we had measurements of type 1 and type 2 markers TNF-α and IgE, respectively, which are commonly seen to be elevated in models of alcohol dependence." (PMID 33347446, 2020). "Excessive TNF-α production—evidence of type 1 responses—and increased IgE levels—evidence of type 2 responses—are hallmarks of alcoholism." (PMID 33347446, 2020). "Meanwhile, Western blot analysis and real-time fluorescence quantitative PCR (rt-PCR) results showed that DHQ was able to reduce the level of tumor necrosis factor-α (TNF-α), block the activation pathway of nuclear factor-κB (NF-κB) in the liver, and effectively reverse the alcohol-induced." (PMID 39124941, 2024). "Alcohol activated the microglia and increased expression of multiple pro-inflammatory cytokines such as tumor necrosis factor α and IL-1β, which may enhance alcohol consumption and contribute to the development of alcoholism." (PMID 36032235, 2022). "The goal of this study was to evaluate the effect of transcutaneous auricular vagus nerve stimulation (taVNS) on PAWS and plasma brain-derived neurotrophic factor (BDNF), interleukin-6 (IL-6), tumor necrosis factor-α (TNF-α), and leptin levels in patients with alcohol dependency." (PMID 34526917, 2021). "Although in acute alcohol induced-liver injury acetaldehyde has been shown to inhibit TNF-α release by Kupffer cells through inhibition of the NF-kB pathway, in chronic alcohol abuse the role of Kupffer cell activation and TNF-α release in promoting liver injury is well established." (PMID 19756185, 2009). "As with the relationship of Klotho with the TNF-α, this result may be interpreted as derived from a compensatory increase of Klotho levels in a context of an increased ROS production (as is the case of alcoholism and, especially, alcoholic cirrhosis)." (PMID 36009045, 2022). "Plasma leptin concentrations were positively correlated with the plasma IL-6, CRP, and TNF-α levels in the present study, which suggests that the role of leptin as a marker of addiction in alcohol-dependent patients may be related to the changes in inflammatory cytokines." (PMID 32265847, 2020). "Moreover, the hydrolyzed peptide of coix seed protein with molecular weight < 5 kDa could retard lipid peroxidation via decreasing the MDA level and increasing the SOD activity in the liver, and might suppress the overexpression of serum TNF-α and IL-β-induced alcohol injury." (PMID 35681289, 2022).
alcoholism (continued). "In conclusion, our results indicate that the suppression of TNF-α secretion and maintenance of hepatic GSH by barley sprouts extract contributed to its overall preventive effects against alcohol-induced liver injury." (PMID 27455313, 2016). "The results revealed that FMT significantly decreased the levels of TNF-α, IL-4 and IL-18, which indicated that FMT could ameliorate the inflammatory reaction in alcohol dependence mice." (PMID 38249454, 2023). "Based on these findings, we hypothesized that taVNS could ameliorate PAWS in alcohol-dependent patients, the mechanism of which may be related to its regulation of plasma BDNF, IL-6, TNF-α, and leptin levels." (PMID 34526917, 2021). "However, an increase in the proinflammatory cytokine TNFα, in addition to the presence of OX-6/MHCII+ cells in the rhinal cortex 7 days after ethanol exposure, was observed, neither of which was seen in previous work in the same model of alcohol dependence in males." (PMID 38338883, 2024).
colon adenocarcinoma (46 papers, 1999 to 2025). "To determine how Sirt1-Tg CSMCs inhibited colonic epithelial regeneration following DSS-induced injury observed in the model, we used the conditioned media (CM) of WT and Sirt1-Tg CSMCs induced with TNF-α to treat human colon adenocarcinoma Caco-2 cells." (PMID 40076434, 2025). "The potential protective effect of MF and FeMF against TNF-α-induced alterations was investigated in a human colonic adenocarcinoma cell line." (PMID 38472817, 2024). "Upregulation of CLDN2 by TNFα was further confirmed in a human colonic adenocarcinoma cell line (Caco2) treated with TNFα (20 ng/mL) or IL-1β (10 ng/mL), respectively." (PMID 37287024, 2023). "IL-8 production of human HT29 colon adenocarcinoma cells following the TNF-α challenge was diminished by luteolin." (PMID 37106972, 2023). "Human clonal colon adenocarcinoma cells (Caco-2) stimulated by tumor necrosis factor-α (TNF-α) were employed in this study." (PMID 35509629, 2022). "In an in vitro study relevant to IBD, butyrate and propionate were found to be more effective than acetate in inhibiting LPS-induced TNFα production from neutrophils and TNFα-mediated NF-κB activation in the human colon adenocarcinoma cell line." (PMID 36235765, 2022). "The aerial parts of P. cablin also inhibited TNF-α in a human promonocytic cell line (U937 cell) and a human colonic adenocarcinoma cell line (HT-29 cells)." (PMID 33785002, 2021). "eIF5A1 is rapidly translocated to the nucleus by tumor necrosis factor α (TNF-α), death receptor activation, or treatment with actinomycin D in colon adenocarcinoma cells." (PMID 34831461, 2021). "The TCM of oesophageal, rectal and colonic adenocarcinoma significantly inhibited levels of TNF-α in DC supernatants (p = 0.004, p = 0.013 and p = 0.026 respectively)." (PMID 32552799, 2020). "The anti-inflammatory activity of NED was also examined using TNF-α-induced HT-29 cells, which are human colonic adenocarcinoma cells with an epithelial morphology." (PMID 32650602, 2020). "Single injection of TNF-α at a dose of 300 μg/kg in the MC38 murine colon adenocarcinoma showed reduced vascular parameters from 2–96 h following treatment." (PMID 24300371, 2012). "The 3-(4-hydroxyphenyl)propanoic acid inhibited the secretion of proinflammatory cytokines, including interleukin-1β (IL-1β), IL-6, and tumor necrosis factor-α (TNF-α), from lipopolysaccharide (LPS)-stimulated Caco-2 cells (human colon adenocarcinoma cell line)." (PMID 39519743, 2024). "This property of the flavonoid was shown in rats, counteracting the effect of a high-fat diet, and in human colonic adenocarcinoma (Caco-2) cells treated with ethanol, polybrominated diphenyl ether, and tumor necrosis factor-alpha (TNF-α) and interferon-gamma (IFN-γ)." (PMID 38998064, 2024). "The potential protective effects of FS and NFS against TNF-α-induced alterations were evaluated in HT-29, a human colonic adenocarcinoma cell line, exposed for 24 h to 5 ng mL−1 TNF-α following a 1-h pre-treatment with or without 0.08 and 0.4 mg mL−1 FS and NFS extracts." (PMID 37047259, 2023). "Bearing in mind the increasing interest in low-grade inflammation and its role in the development of a wide range of inflammation-related disorders, we purposed to track the cytokines secretion in PMNs (TNF-α, IL-8, IL-1β) as well as in human colon adenocarcinoma cell line Caco-2 (IL-8)." (PMID 34834710, 2021). "Additionally, a previous study showed that TNF-α promoted a downregulation of AQP3 expression in human colonic adenocarcinoma (HT-29) cells through inhibition of constitutive transcriptional activity of the AQP3 promoter." (PMID 34267676, 2021). "ROS is involved in TNF-induced necroptosis of human colon adenocarcinoma HT-29 cells." (PMID 34183021, 2021). "The consistent and significant inhibition of DC TNF-α across oesophageal, rectal and colonic adenocarcinoma may be the key way in which DC maturation is dysregulated by GI cancers." (PMID 32552799, 2020).
colon adenocarcinoma (continued). "A recent study demonstrated that propionate, similarly to butyrate, may inhibit the activation of NF-κB in colon adenocarcinoma cell line with a consequent reduction of pro-inflammatory factors expression such as TNF-α and IL-1β in colon tissues." (PMID 32344758, 2020). "As the oesophageal TME appears to be less inhibitory compared to colonic adenocarcinoma, this may have implications for informing immunotherapy, such as DC vaccines, and PD-1/PD-L1 or TNF-α blockade." (PMID 32552799, 2020). "LRG1 expression can be induced by TNF-α, IL-6, and IL-22 in human colon adenocarcinoma cell line." (PMID 32249825, 2020). "Similarly, previous comparative studies revealed that EBN had increased proliferation rate of the human colonic adenocarcinoma cell line (Caco-2 cells) about 135%-215% compared to the control and reduced the percentage of tumor necrosis factor-alpha in vitro." (PMID 31528026, 2019). "Indeed, we previously observed significant cell death rates among human colon adenocarcinoma cells (HT-29 cell line) exposed to supernatants from jacalin-stimulated macrophages, which contained high TNF-α levels." (PMID 28676858, 2017). "According to these results, pathogen-associated molecular patterns (LPS) and damage-associated molecular patterns released from injured epithelial cells (TNF-α) may induce a local inflammatory response in colon adenocarcinoma cells that involve the activation of IL- 36γ." (PMID 40268791, 2025). "Previous study demonstrated that melatonin exposure could decrease mitotic and apoptotic indices in the colonic adenocarcinomas and lower the expression of inflammatory mediators like nuclear factor-κB (NF-κB), tumor necrosis factor (TNF)-α, IL-1β, and STAT3 in the epithelial malignancies." (PMID 31637261, 2019). "This is in contrast to what is observed in human colon adenocarcinoma epithelial cells, HT29, stimulated with TNFα." (PMID 40076925, 2025). "Although AICAR has been reported to be associated with enhanced TNF-stimulated JNK and p38 phosphorylation in human colon adenocarcinoma cells, in BMDMs both A-769662 and AICAR decrease p38 and ERK-MAPK phosphorylation after TNF induction." (PMID 26474486, 2015). "In human colon adenocarcinoma HT-29 cells, knockdown of RIP1 downstream of MLKL blocked TNF-induced necrosis." (PMID 24932290, 2014). "IL-10 does not stimulate or affect IL-8 production by LPS or TNFα induced by human colon adenocarcinoma HT-29 cells, however Bifidobacterium sp." (PMID 33468130, 2021). "Furthermore, the nanodrug CYT-6091, which was created by linking human TNF alpha (rhTNF) and polyethylene glycol (PEG) to the surface of GNPs, was tested in a phase I clinical trial on a variety of solid tumors, including colon adenocarcinoma." (PMID 35127533, 2021). "The CT26 colon adenocarcinoma tumor model is known to be sensitive to TNF therapy and does not require D-GalN sensitization." (PMID 32027657, 2020). "Recent studies on different human colonic adenocarcinomas have demonstrated that ZER had suppressive influence against inflammatory and oxidative stress factors such as generation of free radicals, nitric oxide synthase expression and tumor necrosis factor-α release." (PMID 28974019, 2017).
endometrial cancer (46 papers, 2003 to 2025). Primary or metastatic malignant neoplasm involving the endometrium (mucous membrane that lines the endometrial cavity). "Elevated circulating levels of certain pro-inflammatory cytokines, including interleukin-6 (IL-6), interleukin-8 (IL-8), and tumor necrosis factor-α (TNF-α) have been associated with an increased risk of endometrial cancer." (PMID 40877024, 2025). "TNFα increased the risk of endometrial cancer in the diabetic population (ORQ4 vs. Q1 = 4.176, 95% CI 0.990–17.609, p = 0.052), whereas this effect is not seen in the entire population (ORQ4 vs. Q1 = 0.625, 95% CI 0.412–0.949, p = 0.024; adjusted p = 0.096)." (PMID 38339282, 2024). "In fact, TNF has been associated with established risk factors for endometrial cancer, including increased local estrogen production, increased development of insulin resistance, and type 2 diabetes." (PMID 35628566, 2022). "The plasma concentrations of the proinflammatory cytokines TNF-α and IL-6 positively correlate with BMI, and, in turn, have been directly associated with endometrial cancer promotion and progression." (PMID 35053431, 2022). "Endometrial cancer risk was increased in women with elevated pre-diagnostic concentrations of TNF in a case-control study with 270 cases and 518 controls." (PMID 32805626, 2020). "Epidemiological data on TNF levels in relation to risk of breast, lung and endometrial cancer are also conflicting and scarce." (PMID 32805626, 2020). "To validate our findings on the protein level, we first studied production of CD8+-associated cytokines IFN-γ, TNF-α, and IL-2 in endometrial cancer cytotoxic TIL." (PMID 32471032, 2020). "A case-control study showed that elevated levels of TNF-α and its soluble receptors (sTNFR1 and sTNFR2) were associated with an increased risk of endometrial cancer [TNF-α-odds ratio [OR]: 1.73; sTNFR1-[OR]:1.68; sTNFR2-[OR]:1.53]." (PMID 31440472, 2019). "Elevated levels of TNFα along with its receptors have been strongly associated with a higher risk of endometrial cancer." (PMID 24288542, 2013). "Thus, in endometrial cancer cells, BA probably caused NF-κB inhibition through TNFα inhibition, thereby suppressing cell survival and inducing apoptosis." (PMID 37772231, 2023). "Consistently with our findings, another paper reported that endometrial cancer patients had increased levels of oxidative stress markers, in comparison to controls, and that they were associated with increased values of circulating TNF-α, IL-6, and CRP." (PMID 35053431, 2022). "Similarly, studies incorporating biomarkers (adiponectin, estradiol, interleukin-1 receptor antagonist, tumor necrosis factor-and triglyceride) into the risk prediction model of endometrial cancer have found that they can modestly improve the predictive ability of endometrial cancer." (PMID 31440472, 2019). "Presence of higher levels of adiposity-related inflammatory cytokines as well as factors such as IL-6, TNFα, and C-reactive protein, in addition to lower levels of adiponectin has been implicated as possible contributing factors for initiation and progression of endometrial cancer in women." (PMID 24288542, 2013). "Endometrial cancer is linked to obesity and chronic inflammation, potentially mediated by adipocytokines like adiponectin, leptin, IL6, and TNFα." (PMID 40642843, 2025). "In comparison to normal endometrium used as a reference or calibrator, the expressions of all the adipocytokines—adiponectin, leptin, IL6, and TNFα—were found to be much higher in endometrial cancer tissue." (PMID 40642843, 2025). "TNF-α signaling, especially the TNF-α/NF-κB axis, is disrupted in endometrial cancer and worsens with disease progression." (PMID 37233761, 2023). "This study indicates a significant role of the TNF-α/NF-κB axis in the course of endometrial cancer." (PMID 37233761, 2023).